GPX4 (glutathione peroxidase 4)
Diseases named in the same sentence as GPX4 in open-access papers (continued):
Sharing a sentence is not in itself a finding about the gene and the disease.
tumor (continued). "Moreover, methionine/cystine deprivation caused downregulated the expression of GPX4, an inhibitor of ferroptosis, in tumor tissues." (PMID 37268653, 2023). "Our study showed that NeuroD1 could promote the expression of GPX4, thereby enhancing cell antioxidant capacity and preventing harmful oxidative stress caused by the rapid proliferation of tumor cells." (PMID 38134213, 2023). "In summary, we speculate that SNORA71C promotes the proliferation of tumor cells associated with GPX4 and PTGS2, leading the reducing GSH increased and finally inhibiting ferroptosis in ER+ cells." (PMID 37077773, 2023). "GPX4 deficiency in Treg cells increases the production of mitochondrion-derived superoxide and interleukin-1β that promotes T helper 17 responses, thereby repressing tumor growth and concomitantly potentiating antitumor immunity." (PMID 37795022, 2023). "Interestingly, the loss of GPX4’s function contributes to the selective ferroptosis dependency of cells and tumor relapse, which has been shown in non-small cell lung cancer, pancreatic cancer, prostate cancer, and melanoma cells." (PMID 36675129, 2023). "RSL-3 causes ferroptosis by the direct inhibition of GPX4, indicating that tumor cells that rely heavily on GPX4 might be especially vulnerable to class II FIN treatment." (PMID 35406596, 2022). "A loss of GPX4 might offer a way to selectively kill therapy-resistant tumor cells and prevent relapse." (PMID 35530303, 2022). "GPX4 has been reported to be closely associated with tumors and tumor resistance." (PMID 35906548, 2022). "Additionally, SLC3A2 deficiency suppressed tumor growth in nude mice, and the expression of GPX4 was upregulated in sh-SLC3A2 tumor tissues compared to sh-NC tumor tissues by IHC staining." (PMID 35057861, 2022). "ZEB1, a transcription factor associated with EMT-mediated tumor metastasis, has been shown to promote ferroptosis by directly inhibiting GPX4 activity, as well as in part through ZEB1-induced upregulation of PPARγ, a master regulator of hepatic lipid metabolism." (PMID 35847022, 2022). "Consequently, mice with GPX4-deficient Tregs display reduced tumor burden and concomitantly enhanced antitumor immunity, without showing overt systemic autoimmunity." (PMID 35720275, 2022). "However, M1 subtype with higher anti-tumor activity showed higher resistance to ferroptosis caused by deletion of GPX4." (PMID 36387286, 2022). "The loss of GPX4 function resulted in selective DTPs ferroptotic death and prevented tumour relapse in mice, which suggests that targeting of GPX4 may represent a therapeutic strategy to prevent acquired drug resistance." (PMID 31619007, 2019). "Therefore, the functional inhibition of system Xc− (cysteinyl/glutamate antiporter) or down-regulation of the rate-limiting enzymes of GSH synthesis such as GCLC in tumor cells leads to the loss of GPX4 activity, which in turn induces irreversible lipid peroxidation damage." (PMID 40559667, 2025). "Therefore, inhibiting GPX4 activity or expression may increase the sensitivity of tumor cells to ferroptosis, making them more susceptible to clearance by the immune system." (PMID 39273090, 2024). "Consequently, inhibiting GPX4 renders these tumour cells highly susceptible to ferroptosis." (PMID 38140764, 2024). "Thus, GPX4 inactivation caused by GSH depletion can also induce ferroptosis for tumor treatment." (PMID 38561739, 2024). "Unsurprisingly, other factors that may promote polyunsaturated fatty acid phospholipid (PUFA-PL) synthesis and peroxidation (such as FATP2 and MPO), or that may cause GPX4 inhibition (such as hypoxia in the tumor microenvironment), may also influence the inhibitory activity of tumor PMN-MDSCs." (PMID 36813764, 2023). "It was reported that GPX4 dependence and ferroptosis hypersensitivity could be detected in multiple malignancies under different therapies, which was considered to be associated with acquired therapy resistance and tumor relapse." (PMID 34922551, 2021).
tumor (continued). "Consistently, treatment with DGAT1/2 inhibitors or inducible overexpression of GPX4 in tumor cells significantly resensitizes tumor cells to ferroptosis and ignites the activation of T cells in the TME to inhibit NSCLC progression." (PMID 41259048, 2026). "Mechanistically, it induced sustained ferroptosis by promoting iron accumulation, lipid peroxidation, and GPX4 suppression, while remodeling the tumor immune microenvironment." (PMID 41510171, 2026). "It is noteworthy that the development of anti‐tumor drugs related to the iron death pathway mainly focuses on GPX4, which is responsible for promoting lipid peroxide clearance." (PMID 41126755, 2026). "Ophiopogonin B is extracted from Radix Ophiopogon japonicus and has been shown to reduce tumor volume and induce ferroptosis by blocking the GPX4/xCT system." (PMID 41526983, 2026). "This degradation directly suppresses tumor cell proliferation and downregulates glutathione peroxidase 4 expression to sensitize cancer cells to oxidative damage." (PMID 41803913, 2026). "The GPX4 inhibitor RSI3 triggers immunogenic cell death (ICD) in tumor cells to activate DCs, introducing a new mechanism for inducing anti‐tumor immunity." (PMID 41560416, 2026). "This cascade induces mitochondrial ROS overproduction, glutathione (GSH) depletion, GPX4 inactivation, and lipid peroxidation accumulation, resulting in tumor cell ferroptosis." (PMID 41518487, 2026). "By scaffolding FUS to stabilize GPX4 mRNA, lncRNA-PRLB maintains GPX4 expression and enables tumor cells to evade ferroptotic cell death." (PMID 41783067, 2026). "ZFO exhibits peroxidase- and glutathione oxidase-mimetic activities, catalyzing tumor-derived H2O2 into hydroxyl radical and inhibiting glutathione peroxidase 4, thereby inducing ferroptosis." (PMID 42016759, 2026). "We previously found that persister cells from multiple tumor types and treatments are vulnerable to ferroptosis which can be induced with inhibitors of the lipid hydroperoxidase glutathione peroxidase 4 (GPX4)." (PMID 41481741, 2026). "Yet, other research finds that GPX4 inhibitors can selectively induce ferroptosis in CTLs in in vitro models, thereby promoting tumor cell survival." (PMID 41560416, 2026). "Next, we found that protein content of IL-6 was ~5-fold greater in muscle from wildtype tumour-bearing mice compared to control mice, and GPx4 overexpression prevented this increase in IL-6." (PMID 41854231, 2026). "Inhibiting GLS1 enhances the efficacy of ferroptosis inhibitors in suppressing tumour growth, and simultaneously targeting GPX4 and GPX1 offers a powerful anti‐cancer approach." (PMID 40259435, 2025). "Cox multivariate analysis verified that high levels of GPX4 expression (p = 0.033), clinical stage (p = 0.036), and tumor location (p = 0.036) were strong predictors of prognosis in COAD." (PMID 40746894, 2025). "Based on this, GPX4 inhibitors can effectively suppress the overexpression of GPX4 in tumor cells, thus reactivating ferroptosis and impeding tumor growth." (PMID 40746825, 2025). "Consistently, L. reuteri restored GPX4 expression and reduced the ferroptosis-associated upregulation of TFRC expression in tumor tissues, thereby recapitulating the biochemical fingerprint of I3A treatment." (PMID 41354345, 2025). "Senescent endothelial cells secrete exosomal SLC1A5, which is taken up by tumor cells and suppresses ferroptosis in tumor cells via the EGFR/SRC/YAP1/GPX4 pathway, thereby promoting gastric cancer progression." (PMID 40919170, 2025). "Overexpression of GPX4 in tumor cells inhibits ferroptosis by neutralizing lipid peroxides, promoting tumor survival and metastasis." (PMID 40365295, 2025). "NanoDDSs enhance tumor targeting while minimizing systemic toxicity, as demonstrated by Wang’s team using ROS-responsive lipid nanoparticles (dGPX4@401-TK-12, ~200 nm) for GPX4 degradation-induced ferroptosis." (PMID 40871058, 2025).
tumor (continued). "GPX4-deficient Tregs accumulate lipid peroxides and produce IL- 1β, which activates DCs and CD8 + T cells, thereby fostering anti-tumor immunity." (PMID 40285867, 2025). "This E3 ubiquitin ligase facilitates the ubiquitination and degradation of GPX4, promotes ferroptosis, and suppresses tumor development in vivo." (PMID 41008615, 2025). "GPX4 is a key regulatory factor that reduces the lipid peroxidation level of tumor cells and inhibits the activities of cyclooxygenase and lipoxygenase." (PMID 41189569, 2025). "RSL3 is a small molecule inhibitor of GPX4 that exhibits significant anti-tumor effects against NSCLC in vitro and in vivo." (PMID 40191731, 2025). "The GLS1 inhibitor synergizes with the GPX4 inhibitor to inhibit tumour growth, and dual suppression of GPX4 and GPX1 offers a potent anti‐cancer strategy." (PMID 40259435, 2025). "GPX4 overexpression serves as a biomarker for aggressive tumor behavior, while its inactivation-driven ferroptosis offers a mechanism-guided avenue for anticancer interventions." (PMID 40136465, 2025). "This targeted inhibition effectively impedes the cellular uptake and influx of extracellular cystine, thereby indirectly suppressing GPX4 enzymatic activity and ultimately leading to the highly efficient induction of ferroptosis in tumor cells." (PMID 40260246, 2025). "On the other hand, hypoxia can promote HIF1α-mediated transcription of lactate dehydrogenase (LDH) and SLC7A11, activate intracellular lactate accumulation and cystine uptake, and promote tumor resistance to ferroptosis through the lactate/GPX4 pathway." (PMID 40855044, 2025). "This pathway operates independently of GPX4 and ACSL4 and has been demonstrated to suppress tumor formation, as the loss or mutation of ALOX12 accelerates cancer development in lymphoma models." (PMID 40733290, 2025). "Compared to the sh-NC group, the sh-LINC00958 group showed decreased LINC00958 expression and GPX4 expression in the tumor tissue (p < 0.05), along with elevated iron content, ROS levels, and ACSL4 expression, and reduced GSH levels (p < 0.05)." (PMID 40537877, 2025). "It is noteworthy that CD8+ T cells are significantly more sensitive to GPX4 inhibition than tumor cells: ACSL4 knockdown significantly reduces ferroptotic cell death, while FSP1 overexpression provides protection through the CoQ10 regeneration pathway." (PMID 40535125, 2025). "The inhibition of FTO reduces GPX4 expression and sensitizes tumor cells to ferroptosis, providing a novel epitranscriptomic mechanism for targeting GPX4 in HNSCC." (PMID 40650229, 2025). "On the one hand, immunosuppressive cells such as M2 macrophages, T regulatory (Treg) cells, and tumor-infiltrating neutrophils (TINs) rely on GPX4 and other factors to prevent ferroptosis and maintain their pro-tumor activity." (PMID 40328736, 2025). "In summary, our study demonstrates that Huaier effectively induces ferroptosis in NSCLC by simultaneously modulating the SLC7A11/GPX4 axis and ferritinophagy, thereby exerting its anti-tumor effects both in vitro and in vivo." (PMID 40623982, 2025). "Research on the relevant molecular mechanism by which NAT10 regulates ferroptosis revealed that NAT10 affected ferroptosis, which is closely related to tumor cells, by influencing the key regulatory molecules GPX4 and NFE2L1 of ferroptosis." (PMID 41189569, 2025). "The loss of glutathione peroxidase 4 (GPX4) in T cells can promote ferroptosis and targeting to eliminate GPX4 in Tregs can attenuate tumor growth and enhance anti-tumor immunity." (PMID 40064873, 2025). "The excessive ROS is expected to induce glutathione peroxidase 4 (GPX4) down-regulation, trigger ferroptosis, and disrupt the homeostasis of tumor lipid metabolism." (PMID 40968370, 2025). "Tumors undergoing lipid oxidative stress release immunogenic cell death signals such as high mobility group box 1 (HMGB1), a mechanism critical for GPX4-mediated tumor targeting." (PMID 40001204, 2025).
tumor (continued). "Meanwhile, ferroptotic cell death is intensified through the inactivation of GPX4 by RSL3 released from DP‐HBN/RA to acidic conditions in the tumor microenvironment." (PMID 39721034, 2025). "Red ginseng polysaccharide (RGP), a bioactive compound found in the commonly used medicinal plant Panax ginseng C. A. Meyer (Araliaceae), triggers ferroptosis by reducing the expression of GPX4, resulting in anti-tumor activities." (PMID 40191731, 2025). "Since IDO1 is crucial for kynurenine metabolism in tumor cells, how GPX4 regulates IDO1 levels via ROS was first investigated." (PMID 40365295, 2025). "In the context of tumor or cancer eradication through ferroptosis, focusing on the inhibition of GPX4, the primary regulator of ferroptosis, is currently the preferred strategy." (PMID 40248093, 2025). "Together, these results revealed that Mn-S1N3/SAE combined with laser irradiation effectively induced tumor ferroptosis via the accumulation LPO and the inactivation of GPX4, suggesting its potential for use in tumor therapy." (PMID 41215762, 2025). "In tumor models, functional inhibition of GPX4 induces upregulation of 12‐LOX and COX1 expression, thereby triggering characteristic inflammatory responses." (PMID 40919133, 2025). "Conversely, tumour‐specific GPX4 degradation enhances ferroptosis, boosting the anti‐tumour immune response in pancreatic cancer." (PMID 40696496, 2025). "For example, in lung adenocarcinoma, dual knockout of Nrf2 and GPX4 significantly raises tumor cell mortality rates." (PMID 40599237, 2025). "Exhibits anti-tumor and anti-neuroinflammatory effects in a GPX4-dependent manner through the TLR4/NF-κB pathway." (PMID 40153574, 2025). "Elevated ROS levels and decreased GPX4 expression were further validated in tumor tissues from treated mice." (PMID 40213972, 2025). "Lupeol, a triterpenoid found in fruits and vegetables, has been shown to potentiate ferroptosis by inhibiting GPX4 activity and destabilizing redox balance, further contributing to anti-tumor effects in NPC." (PMID 41373599, 2025). "Following conditioning with a sublethal irradiation dose, MC38 tumor-bearing CD90.1+ mice received tumor-reactive polyclonal CD90.2+ WT or GPX4–/– CD8+ T cells followed by treatment further with or without α4-1BB." (PMID 40178905, 2025). "EBV activates the Nrf2/Keap1–SLC7A11/GPX4 axis, enhancing antioxidant defenses and suppressing ferroptosis, which contributes to both tumor progression and therapy resistance." (PMID 41373599, 2025). "Given the pivotal role of GSH metabolism in tumor biology, GPX4 inhibition represents an emerging therapeutic strategy." (PMID 40919133, 2025). "While the GPX4/GSH levels are correlated preferentially with T cell stemness, the specific role of GSH/GPX4 in T cell differentiation and exhaustion within the tumor requires further investigation, particularly in the context of 4-1BB costimulation." (PMID 40178905, 2025). "DNAJB6 exerts a dual tumor-suppressive role by stabilizing GPX4 and activating the signaling AKT1 pathway." (PMID 41293165, 2025). "In line with the results we observed previously, tumor-reactive GPX4–/– CD8+ T cells lost their antitumor activity with fewer tumor-infiltrating transferred CD8+ T cells and decreased IFN-γ production and Ki67 expression compared with control CD8+ T cells." (PMID 40178905, 2025). "Ferroptosis disrupts such reprogramming, particularly through suppression of glutathione peroxidase 4, which can increase oxidative stress sensitivity and hinder tumor metastasis." (PMID 41198650, 2025). "Along with the released RSL3, a GPX4‐targeted FINs inhibits the adaptive upregulation of the antioxidant enzyme GPX4, thereby reducing potent tumor radioresistance and enhancing ferroptosis to suppress tumor growth." (PMID 39721034, 2025). "Immunohistochemical analysis revealed that GPx4 was overexpressed in distant metastasis compared with primary tumor and adjacent normal tissues." (PMID 39908861, 2025).
tumor (continued). "Certain selenoproteins, such as glutathione peroxidase 4 (GPX4), have notable antioxidant effects and play a vital role in the homeostasis of tumor cells." (PMID 40750759, 2025). "In BRCA1-deficient OC cells, PARP inhibitors (PARPi) can induce ferroptosis, and their combination with GPX4 inhibitors exhibits significant synergistic anti-tumor effects." (PMID 40539051, 2025). "The upregulation of the Xc-/GSH/GPX-4 axis is also an important mechanism for tumor cells to escape ferroptosis." (PMID 40169575, 2025). "CD8 T-cell-derived lFN-γ secretion cooperated with free arachidonic acid to promote ferroptosis sensitivity in tumor cells, and activated regulatory T cells (Treg) were sensitive to Treg-selective Gpx4 deletion, allowing for improved anti-tumor immunity." (PMID 40281125, 2025). "Utilizing this, targeted reduction of GPX4 expression in tumor cells can be regarded as a crucial tumor therapeutic approach." (PMID 40969276, 2025). "In NPC models, both compounds have been used to demonstrate that blockade of the cystine–GSH–GPX4 axis sensitizes tumor cells to ferroptotic death, particularly in GPX4-low or xCT-addicted phenotypes." (PMID 41373599, 2025). "Following FABP5 inhibition via nanocarriers, C11‐BODIPY fluorescence assays revealed a significant increase in lipid peroxidation and a corresponding decrease in GPX4 expression in tumor cells, indicating that FABP5 inhibition enhances RFA‐induced ferroptosis." (PMID 40956367, 2025). "This discovery has shifted DHODH from being regarded solely as a nucleotide metabolic enzyme to being recognized as a critical determinant of ferroptosis sensitivity, particularly in GPX4-low tumor contexts." (PMID 41369379, 2025). "Irradiation also induces adaptive responses involving SLC7A11 or GPX4, inhibiting radiation-induced ferroptosis and promoting tumor cell survival, leading to radioresistance." (PMID 39990661, 2025). "The abundance of GPX4 in tumor cells can be related to its methylated level due to increased levels of histone methylation in H3K4me3 on its promoter that results in the inhibition of ferroptosis." (PMID 41339932, 2025). "Through the upregulation of antioxidant metabolism pathways, such as GPX4 and glutathione synthesis, and modulation of lipid metabolism, tumor cells adapt to environments with high iron levels and oxidative stress." (PMID 40416987, 2025). "A deeper understanding of context-specific dependencies, such as the interplay between DHODH and GPX4 levels, the tumor lipidome, and immune microenvironmental cues, will be critical for rational clinical application." (PMID 41369379, 2025). "This study establishes a basis for combining ERBB3 inhibition with ferroptosis inducers like GPX4 inhibitors to achieve increased anti-tumor effects." (PMID 40846695, 2025). "The S-palmitoylation of GPX4 facilitates its stability and enhances ferroptosis resistance in tumor cells." (PMID 41318030, 2025). "The research found that the LINC01004/hsa-miR-125b-2-3p/HSPA4 axis inhibits ferroptosis in HCC cells by affecting GPX4 activity and iron metabolism, thereby influencing tumor progression." (PMID 40386780, 2025). "Despite the expression of ACSL4 and the inhibition of GPX4, tumor cells continue to exhibit resistance to ferroptosis, indicating the presence of alternative resistance mechanisms." (PMID 40248093, 2025). "The administration of baicalein (10, 20 mg/kg, i.e., every two days for two weeks) significantly decreased the formation of tumors in a CRC xenograft mice model by blocking the JAK2/STAT3/GPX4 axis in tumor tissue." (PMID 40969276, 2025). "The survival, expansion, and effector function of CD8+ T cells, a core effector cell population in anti-tumor immunity, are precisely regulated by GPX4." (PMID 40535125, 2025). "Research has revealed that the selenoproteins GPX2 and GPX4 exert the most significant impact on the tumor microenvironment." (PMID 41323827, 2025).